CTSL (cathepsin L)
Diseases named in the same sentence as CTSL in open-access papers (continued):
Sharing a sentence is not in itself a finding about the gene and the disease.
cervical carcinoma (16 papers, 2009 to 2025). A carcinoma arising from either the exocervical squamous epithelium or the endocervical glandular epithelium. "The expression of CTSL took the leading position in thyroid cancer, followed by liver and cervical cancer in a HPA data set (CAB000459)." (PMID 35155389, 2022). "Analysis of the lysosomal cysteine proteases in the human cervical cancer cell lines indicated that this lysoptosis-like death resulted in the release of active CTSL into the cytoplasm of SW756B3-KO cells." (PMID 35022507, 2022). "LMP induced by TNF-alpha has been shown to be dependent on CTSB and the cationic amphiphilic drug resveratrol has been shown to induce LMP in cervical cancer cells that are dependent on autophagy and CTSL." (PMID 33919392, 2021). "Another study indicated that cathepsin L acts as a death signal integrator and cytosolic cathepsin L regulated the cytochrome c release and caspase-3 activity in cervical cancer cells." (PMID 32069858, 2020). "The positive transcriptional regulation of cathepsin L (CTSL) by the activity of COP9 signalosome subunit 6 (CSN6) deubiquitinase was identified in cervical cancer cells." (PMID 32545524, 2020). "For example, cervical cancer cells with knockdown of the cystine protease inhibitor SERPINB3 (squamous cell carcinoma antigen 1, SCCA1) are more sensitive to ionizing radiation, mainly due to lysosomal-like death caused by enhanced CTSL activity." (PMID 36552871, 2022).
diabetes (14 papers, 2010 to 2024). "Elevated cathepsin L levels are known to contribute to diabetes complications, such as kidney damage and vision loss." (PMID 39150053, 2024). "Aberrant levels of cathepsin L (Cts L), a ubiquitously expressed endosomal cysteine protease, have been implicated in many diseases such as cancer and diabetes." (PMID 35355937, 2021). "Pathological conditions implicated in CTSL are viral or bacterial infection and others such as invasion and metastasis of tumors, atherosclerosis, renal diseases, and diabetes." (PMID 34442377, 2021). "Here, we demonstrate elevated blood CTSL levels in individuals with diabetes, facilitating SARS-CoV-2 infection." (PMID 39150053, 2024). "While cathepsin L is downregulated in diabetes, and furin has been shown to be both up- and downregulated in serum, expression of the TMPRSS2 in cardiomyocytes increases in diabetes." (PMID 39273582, 2024). "Emerging evidence links cathepsins, notably CTSL, to metabolic disorders like obesity and diabetes, as well as diabetic complications." (PMID 39150053, 2024). "Previous research identified a link between an enzyme called cathepsin L and more severe COVID-19 in people with diabetes." (PMID 39150053, 2024). "Significant positive associations were found between higher plasma ACE2 and cathepsin L1, body mass index (BMI), triglycerides, liver fat, hypertension, CVD, blood pressure, and diabetes." (PMID 35387486, 2022). "Our results were consistent with a previous study that reported the upregulation of mRNA expression of LC3, Gabarapl1, and Cathepsin L in the skeletal muscle of diabetic rats and uremia rats induced by subtotal nephrectomy." (PMID 24303049, 2013). "On the other hand, it would be helpful for diagnosis of spontaneous diabetes in NOD mice to measure cathepsin L expression in the peripheral T cells." (PMID 20877570, 2010). "Here it was found that specific inhibition of cathepsin L affords strong protection from cyclophosphamide (CY)-induced insulitis and diabetes of NOD mice at the advanced stage of CD8+ T cell infiltration via inhibiting granzyme activity." (PMID 20877570, 2010). "The increased risk remained significant for KIM-1, UPAR, MMP12, cathepsin L1, TNFR2, and CX3CL1 after adjustments for cardiovascular risk factors (i.e., diabetes, systolic blood pressure, blood lipids, use of blood pressure or lipid-lowering medications and waist circumference)." (PMID 31114450, 2019). "Targeting these CD8+ T cells using cathepsin L inhibitor could be a strategy for the prevention and cure of diabetes in the near future." (PMID 20877570, 2010). "Moreover, the gene targeting for cathepsin L with application of in vivo siRNA administration successfully prevented CY-induced diabetes of NOD mice." (PMID 20877570, 2010). "Therefore, we propose that diabetes may promote COVID-19 infection through multiple factors, and CTSL is only one of several important factors." (PMID 39150053, 2024). "We also identified significant sex heterogeneity for the associations with cathepsin L1, BMI, triglycerides, and diabetes: The ACE2 associations with BMI and triglycerides were stronger in men, whereas the associations with cathepsin L1 and diabetes appeared to be stronger in women." (PMID 35387486, 2022). "As it was reported that cathepsin L-deficient NOD mice are protected from insulitis and diabetes due to the increased number of regulatory T (Treg) cells in the periphery through the defective thymic selection, the therapeutic application with cathepsin inhibitor may be clinically useful." (PMID 20877570, 2010). "We also observed a strongly correlation between CTSL activity/concentration and other chronic comorbidities like hypertension and coronary heart disease (CHD), especially diabetes." (PMID 39150053, 2024).
diabetes (continued). "In laboratory experiments, cells exposed to glucose or fluid from the blood of people with diabetes were more easily infected with SARS-CoV-2, with cells genetically modified to lack cathepsin L being more resistant to infection." (PMID 39150053, 2024). "A recent study targeting cathepsin L has confirmed that cathepsin L-knockout mice do not develop podocyte injury and glomerular damage during diabetes." (PMID 32106480, 2020). "In addition to CTSL, there may be other bioactive factors involved in mediating SARS-CoV-2 infection in patients with diabetes." (PMID 39150053, 2024).
glioblastoma (14 papers, 2014 to 2025). The most malignant astrocytic tumor (WHO grade IV). "CTSL, which cleaves intracellular C3 into biologically active C3a and C3b, has been reported to contribute to glioblastoma malignancy, which supports the role of proteases in mediating glioblastoma invasiveness." (PMID 38894892, 2024). "Cathepsin B(CTSB) and cathepsin L (CTSL) is also strongly expressed in various cell clusters in the glioblastoma microenvironment." (PMID 36552760, 2022). "By contrast, human glioblastoma clones transfected with cathepsin L constructs that displayed increased cathepsin L activity were significantly more invasive." (PMID 27127880, 2016). "The elevated CTSL mRNA level may suggest intracellular complement activation in glioblastoma tumors." (PMID 38894892, 2024). "Thus, inhibition of CTSL activity reduced glioblastoma cell survival and increased cell death via apoptosis in vitro using human glioma cell lines." (PMID 38894892, 2024). "A recent study showed that CTSL might promote chemoresistance by their ability to resist various apoptotic stimuli in glioblastoma Cells, however the study was about brain cancer and the case scale was small." (PMID 25384089, 2014). "Exposing human glioblastoma cells to Transforming Growth Factor-β (TGF-β) for 24 h resulted in increased mRNA levels of C3, C3aR, CTSL, and other growth factors." (PMID 38894892, 2024).
neuroblastoma (12 papers, 2015 to 2025). Neuroblastoma (NB) is the most common solid, extracranial childhood tumor. "Significant reduction in the lysosomal degradation capacity, substantially enlarged lysosomes, and increased lysosome number were observed in the CTSB and CTSL double knockout human neuroblastoma cells." (PMID 35806091, 2022). "Here, we show that CtsB/L inhibition in CHO and in human neuroblastoma SH-SY5Y cells as well as CtsB and CtsL genetic depletion also affects NPC1 and/or NPC2 and causes their sequestration and accumulation of intracellular free cholesterol." (PMID 27902765, 2016). "To address a possible common role of highly expressed and functional important CTS proteases, we generated CTSB-, CTSD-, CTSL-, and CTSBDL-triple deficient (KO) human neuroblastoma-derived SH-SY5Y cells and CTSB-, CTSD-, CTSL-, CTSZ and CTSBDLZ-quadruple deficient (KO) HeLa cells." (PMID 38775843, 2024). "However, the potential roles and molecular mechanisms of CTSL in chemoresistance in neuroblastoma (NB) are still unclear." (PMID 36133820, 2022). "In contrast, it was demonstrated that CTSL expression and nuclear translocation induced by the neurotoxin 6-OHDA is a mechanism that inhibits autophagy in SH-SY5Y neuroblastoma cells." (PMID 33919392, 2021). "Furthermore, targeted inhibition of CTSL in a human neuroblastoma cell line blocked activation of caspase-3 and PARP-1, similarly to our observations in human primary macrophages, in which inhibition of CTSL influenced autophagy but was unable to induce apoptosis." (PMID 32927704, 2020).
atherosclerosis (10 papers, 2021 to 2026). A disease characterized by the build-up of fatty material and calcium deposition in the arterial wall resulting in partial or complete occlusion of the arterial lumen. "Our findings that CTSL activates cellular senescence via an atherosclerosis-associated fSNP on the CDKN2A/B locus fully support the senescence theory in the development of atherosclerosis." (PMID 38944813, 2024). "Particularly, studies from CTSL-deficient mice concluded that CTSL plays a direct role in atherosclerosis." (PMID 38944813, 2024). "Interestingly, both LIF and cathepsin L have been implicated in the development and progression of vascular diseases such as abdominal aortic aneurysm and atherosclerosis." (PMID 34779136, 2022). "Cathepsin L (CTSL) has been implicated in aging and age-related diseases, such as cardiovascular diseases, specifically atherosclerosis." (PMID 38944813, 2024). "Our post-GWAS functional analysis revealed that cathepsin L (CTSL) is an upstream regulator of CUX1, and it induces p16INK4a-dependent and atherosclerosis-associated senescence by indirectly activating CUX1 transcription in a process that requires its proteolytic activity." (PMID 42210653, 2026). "Besides CTSL, there are other cathepsins, including cathepsins B, D, X, C, K, and S, that were reported to be involved in atherosclerosis." (PMID 38944813, 2024). "Consistently, an upregulation of both CTSL and NICD, along with elevated cellular senescence in the plaques isolated from patients with atherosclerosis, was observed." (PMID 42210653, 2026). "Besides CTSK, other members of the cathepsin family, including cathepsin B (CTSB) 52, cathepsin S (CTSS) 53, cathepsin L (CTSL) 54, and cathepsin C (CTSC) 55, also play a critical role in the development of atherosclerosis." (PMID 35673565, 2022). "Thus, while our studies identify a non-canonical Notch1 pathway that can be activated by CTSL in a ligand-independent fashion to induce senescence, our findings also reveal a role of senescence in the development of atherosclerosis." (PMID 42210653, 2026).
colorectal cancer (10 papers, 2008 to 2023). A primary or metastatic malignant neoplasm that affects the colon or rectum. "It is noteworthy that the overexpression of CTSL and CTSB has also been implicated in the progression of colorectal cancer." (PMID 31824841, 2019). "More specifically, nuclear cathepsin L accelerates cell cycle progression of HCT116 cells which are hyper-proliferative colorectal carcinoma cells." (PMID 26594658, 2015). "In contrast, the RKO cell line showed simultaneous high expression of inactive (30 kDa, single chain) cathepsin L and a lower level of active legumain, suggesting that these cysteine proteases are subjected to mutual activation in colorectal cancer cell lines." (PMID 23326369, 2013). "We found that by promoting HMGB1 cytosolic translocation and inhibition of Beclin-1-PI3K-III core complex formation through the MEK/ERK1/2 pathway, naphplatin modulates CTSL and autophagy-lysosome function and enhances its sensitivity towards colorectal cancer." (PMID 37537587, 2023). "All these results suggest that naphplatin can promote HMGB1 cytosolic translocation and inhibits Beclin-1-PI3K-III core complex formation through the MEK/ERK1/2 pathway to modulate CTSL and autophagy-lysosome function, which therefore enhances the sensitivity of colorectal cancer to naphplatin." (PMID 37537587, 2023). "In colorectal cancer, CTSL is reported to be one of the genes involved in immunosuppression." (PMID 34923982, 2021). "However, research examining colorectal cancer has identified both CTSL and CTSV in the nuclear compartment, therefore it is plausible that redundancy may exist in certain models." (PMID 38026973, 2023). "Obviously, high expression of the four genes (DDX56, CTSL, ZC3H12D, and PSMC5) could promote the expression of PD-L1 as they have been proven to be promising biomarkers and immunotherapy targets in a variety of tumors, including colorectal cancer, NSCLC, and gastric cancer." (PMID 35647031, 2022).
gastric cancer (10 papers, 2007 to 2023). A primary or metastatic malignant neoplasm involving the stomach. "Mechanistic studies revealed that FOXO3a increased cathepsin L promoter activation, and cathepsin L overexpression repressed E-cadherin expression, causing gastric cancer cells to undergo epithelial-mesenchymal transition (EMT)." (PMID 27127880, 2016). "Moreover, cathepsin L overexpression represses the expression of E-cadherin, causing gastric cancer cells to undergo the epithelial-mesenchymal transition." (PMID 28402938, 2017). "In a co-culture of CTSL-knocked-down gastric cancer cells with endothelial cells, a reduction in tubule formation was observed whereas CTSL overexpression led to increased tubule formation." (PMID 36289617, 2022). "Taking into account the observed overexpression of CTSL in HCC and its function in ECM degradation, these data in gastric cancer suggest that CTSL also stimulates angiogenesis in HCC." (PMID 36289617, 2022). "Forkhead box O3A has been shown to increase cathepsin L promoter activity, leading to an increase in cathepsin L expression and facilitating gastric cancer cell migration and invasion." (PMID 28402938, 2017). "To further demonstrate the molecular mechanisms by which cathepsin L promotes metastasis in gastric cancer, we analyzed E-cadherin expression in FOXO3a-OE and FOXO3a-OE-CTSL-KD cells by western blotting." (PMID 27127880, 2016). "We detected the expression levels of FOXO3a and cathepsin L in 20 tissue microarray blocks containing 289 gastric cancer tissues (stage II/III) by immunohistochemistry (IHC)." (PMID 27127880, 2016). "Bivariate correlation analysis confirmed that the expression of cathepsin L was significantly positively correlated with FOXO3a expression in gastric cancer tissues." (PMID 27127880, 2016). "Here, we report that FOXO3a overexpression promoted migration and invasion of gastric cancer cells by upregulating cathepsin L. FOXO3a knockdown suppressed migration and invasion and also downregulated cathepsin L expression in gastric cancer cells." (PMID 27127880, 2016). "In our study, we found that the expression of E-cadherin was correspondingly downregulated with increased levels of cathepsin L in FOXO3a-overexpressing gastric cancer cells, which is consistent with a previous report." (PMID 27127880, 2016). "The results of IHC staining showed that 70.2% of the gastric cancer tissues with high expression of cathepsin L displayed high FOXO3a expression." (PMID 27127880, 2016). "It has been reported that cathepsin L is expressed and secreted by gastric cancer and other types of tumors." (PMID 27127880, 2016). "The mechanisms by which CTSL has promoted the angiogenesis of gastric cancer (GC), however, remains unclear." (PMID 32388635, 2020). "Here, we demonstrated that FOXO3a promotes the migration and invasion of gastric cancer through induction of cathepsin L. However, recent publications have reported that increased FOXO3a expression may indicate good prognosis in patients with gastric cancer." (PMID 27127880, 2016). "Therefore, the in vivo results further confirmed that FOXO3a promotes gastric cancer metastasis by inducing cathepsin L expression." (PMID 27127880, 2016). "CTSB and CTSL were reported to be elevated in gastric carcinoma and correlated with its malignant property, but specific expression of neither CTSB or CTSL in sig-type GC-derived cell lines could be detected." (PMID 23451082, 2013).
gastric cancer (continued). "To determine whether upregulated expression of cathepsin L contributes to FOXO3a overexpression-promoted migration and invasion in gastric cancer cells, we transfected cathepsin L-specific knockdown constructs into FOXO3a-overexpressing SGC7901 and MKN28 cells." (PMID 27127880, 2016). "However, when cathepsin L was knockdown in FOXO3a-OE cells, expression of E-cadherin was increased, indicating that cathepsin L cleaves E-cadherin and participates in EMT of gastric cancer cells during the metastatic process." (PMID 27127880, 2016). "Interestingly, in Gastric cancer (GC), VEGF-D transcription was facilitated by proteolytic activation of transcriptional factor CDP/Cux p200 by protease cathepsin L (CTSL)." (PMID 37686121, 2023).